FER (FER tyrosine kinase)
Description:
Tyrosine-protein kinase that acts downstream of cell surface receptors for growth factors and plays a role in the regulation of the actin cytoskeleton, microtubule assembly, lamellipodia formation, cell adhesion, cell migration and chemotaxis. Acts downstream of EGFR, KIT, PDGFRA and PDGFRB. Acts downstream of EGFR to promote activation of NF-kappa-B and cell proliferation. May play a role in the regulation of the mitotic cell cycle. Plays a role in the insulin receptor signaling pathway and in activation of phosphatidylinositol 3-kinase. Acts downstream of the activated FCER1 receptor and plays a role in FCER1 (high affinity immunoglobulin epsilon receptor)-mediated signaling in mast cells. Plays a role in the regulation of mast cell degranulation. Plays a role in leukocyte recruitment and diapedesis in response to bacterial lipopolysaccharide (LPS). Plays a role in synapse organization, trafficking of synaptic vesicles, the generation of excitatory postsynaptic currents and neuron-neuron synaptic transmission. Plays a role in neuronal cell death after brain damage. Phosphorylates CTTN, CTNND1, PTK2/FAK1, GAB1, PECAM1 and PTPN11. May phosphorylate JUP and PTPN1. Can phosphorylate STAT3, but the biological relevance of this depends on cell type and stimulus.
Synonyms: TYK3; PPP1R74; p94-Fer
Tractability: Small molecule: a high-quality ligand is known; it belongs to a druggable protein family. Antibody: UniProt places it where antibodies can reach, with medium confidence; its Gene Ontology location is reachable by antibodies, with medium confidence. PROTAC: it is named in the literature on targeted protein degradation; UniProt records ubiquitination sites on it; ubiquitination databases record sites on it; its protein half-life has been measured; a small molecule that binds it is known.
Target class: Kinase; Protein Kinase; Enzyme; Tyrosine protein kinase Fer family; TK protein kinase group
Safety:
Unwanted effects reported when the protein is acted on. In parentheses: how it was acted on, where the effect was seen, and who reports it.
cardiac arrhythmia (cardiovascular system; source: Lamore et al. (2017))
Gene: Protein-coding gene on chromosome 5 (108,747,841 to 109,196,841, forward strand). Ensembl gene ENSG00000151422.
Subcellular location: Cytoplasm; Cytoplasm, cytoskeleton; Cell membrane; Cell projection; Cell junction; Membrane; Nucleus; Cytoplasm, cell cortex
Subcellular location (Human Protein Atlas): Cytosol
Pathways (Reactome):
Signal Transduction: Signaling by SCF-KIT
Gene Ontology:
Molecular function: epidermal growth factor receptor binding; lipid binding; non-membrane spanning protein tyrosine kinase activity; protein binding; protein tyrosine kinase activity; ATP binding; protein kinase activity; protein phosphatase 1 binding
Biological process: cellular response to macrophage colony-stimulating factor stimulus; cytokine-mediated signaling pathway; interleukin-6-mediated signaling pathway; microtubule cytoskeleton organization; peptidyl-tyrosine phosphorylation; positive regulation of actin filament polymerization; positive regulation of cell migration; positive regulation of cell population proliferation; protein autophosphorylation; regulation of epidermal growth factor receptor signaling pathway; regulation of lamellipodium assembly; tyrosine phosphorylation of STAT protein; actin cytoskeleton organization; cell adhesion; cell-cell adhesion mediated by cadherin; cellular response to reactive oxygen species; chemotaxis; diapedesis; extracellular matrix-cell signaling; Fc-epsilon receptor signaling pathway; insulin receptor signaling pathway; intracellular signal transduction; Kit signaling pathway; negative regulation of mast cell activation involved in immune response; platelet-derived growth factor receptor signaling pathway; and 15 more
Cellular component: actin cytoskeleton; cell junction; chromatin; cytoplasm; cytoplasmic side of plasma membrane; cytosol; lamellipodium; microtubule cytoskeleton; nucleus; plasma membrane; adherens junction; anchoring junction; cell cortex; cytoskeleton; membrane; protein-containing complex
Genetic constraint (gnomAD): Loss-of-function variants: 44 observed, 78.27 expected, observed/expected ratio (o/e) 0.56, 90% interval 0.44 to 0.72. The upper end of that interval is the gene's LOEUF score, 0.72, which puts it in group 2 of 6, group 1 being the genes least tolerant of losing a copy. Missense variants: 728 observed, 784.15 expected, observed/expected ratio (o/e) 0.93, 90% interval 0.87 to 0.99. Synonymous variants: 262 observed, 264.59 expected, observed/expected ratio (o/e) 0.99, 90% interval 0.89 to 1.1.
Homologues: Orthologues: chimpanzee FER (100% identical), macaque FER (99% identical), dog FER (96% identical), pig FER (95% identical), rat Fer (93% identical), mouse Fer (93% identical), guinea pig FER (92% identical), tropical clawed frog fer (81% identical), zebrafish fer (77% identical). Paralogues in human: FES (51% identical), YES1 (22% identical), SRC (22% identical), FYN (22% identical), ABL1 (21% identical), ABL2 (21% identical), TEC (21% identical), LCK (21% identical), LYN (21% identical), FGR (21% identical), HCK (20% identical), FRK (20% identical), and 20 more.
Diseases named in the same sentence as FER in open-access papers:
FER is named in the same sentence as 54 diseases in open-access papers, as found by Europe PMC text mining. Sharing a sentence is not in itself a finding about the gene and the disease. The quoted sentences say what the papers report.
prostate carcinoma (10 papers, 2013 to 2025). A carcinoma that arises from epithelial cells of the prostate gland. "When fused with FER, MAN2A1 transforms into an oncogene; around 80% of prostate cancer patients with MAN2A1-FER have exhibited a dismal clinical prognosis according to earlier studies." (PMID 38627854, 2024). "Gene ontology analysis of differentially expressed genes revealed that lack of Sost in the bone microenvironment up-regulated several genes associated with the GO term “chemotaxis” including MET, PDGFA, FER, NRP2, and EZR in prostate cancer." (PMID 27600237, 2015).
hepatocellular carcinoma (6 papers, 2019 to 2023). A malignant tumor that arises from hepatocytes. "In addition, the SSBP2 (single-stranded DNA binding protein 2)–FER fusion and the MAN2A1 (mannosidase alpha class 2A member 1)–FER fusion have also been identified in leukemia and hepatocellular carcinoma patients, respectively." (PMID 37196766, 2023).
Sepsis (6 papers, 2016 to 2025). Sepsis is defined as life-threatening organ dysfunction caused by a dysregulated host response to infection. "Specifically, Rautanen and colleagues analyzed 28-day mortality in patients with pneumonia, linking the FER tyrosine kinase (FER) gene variation with reduced risk for death from sepsis." (PMID 36335405, 2022). "A recent genome-wide association study showed that a genetic variant within the FER gene is associated with survival in patients with sepsis due to pneumonia." (PMID 28851893, 2017). "A recent genome-wide association study has shown that a genetic variant within the intronic region of the FER gene, rs4957796, is associated with survival in patients with sepsis due to pneumonia." (PMID 28851893, 2017). "We identified no overlap between the cis or trans-eQTL that we detected in sepsis and the association we previously found with sepsis outcome, which involved an intronic variant located in the FER gene." (PMID 26917434, 2016). "Our EMSA assays on a SNP located within FER locus also suggested that some of these sepsis associated SNPs may affect more than one causal genes." (PMID 31475010, 2019). "This observational study addresses the question of whether the FER polymorphism rs4957796 is associated with 90-day survival in patients with sepsis-associated ARDS due to pneumonia and its association with the severity of ARDS (mild, moderate, and severe)." (PMID 28851893, 2017). "Additionally, the FER gene influences leucocyte recruitment and intestinal barrier dysfunction in response to bacterial lipopolysaccharide, which may explain its association with sepsis survival." (PMID 40168842, 2025). "In this systematic review, we found that the FER gene (rs4957796) was significantly associated with 28-day survival in patients with sepsis due to pneumonia and the FLT1 gene (rs9508032) with sepsis-associated ARDS." (PMID 40168842, 2025). "For instance, the presence of the s4957796 SNP in the FER gene was found to significantly improve survival in sepsis patients, possibly through the role of FER in the regulation of cell adhesion, leukocyte recruitment and intestinal barrier dysfunction." (PMID 33961170, 2021). "However, only one study identified a genome-wide significant association at non-coding SNPs in the intron of Fps/Fes related tyrosine kinase (FER) gene in patients with 28 day survival of sepsis due to pneumonia." (PMID 31475010, 2019).
ovarian carcinoma (5 papers, 2018 to 2022). A malignant neoplasm originating from the surface ovarian epithelium. "This was supported by the observation that FER was ubiquitously expressed in ovarian cancer cell lines and strongly expressed in more than a third of 130 high-grade serous ovarian cancers (HGSOCs)." (PMID 29396402, 2018). "Our data identify FER tyrosine kinase as a plausible target for therapy that acts in synergy with one of the most commonly used chemotherapeutic drugs in the treatment of ovarian cancer." (PMID 29396402, 2018). "Inactivation of FER using the inhibitors TAE684 or WZ-4-49-822 in two independent ovarian cancer cell lines (SKOV3 and OVCA432) induced a significant increase in microtubule length in a dose-dependent manner." (PMID 29396402, 2018). "In contrast, FES, the only other family member of FER, was undetectable at mRNA level in ovarian cancer cell lines." (PMID 29396402, 2018). "It was reported that FER regulated GAB1 and MET phosphorylation and activated SHP2-ERK signaling in ovarian cancer." (PMID 34295819, 2021). "Thus, it is possible that FER might also phosphorylate CRMP1 or CRMP4 at Y479 and Y499 in ovarian cancer cells since these two sites are highly conserved." (PMID 29396402, 2018).
breast carcinoma (4 papers, 2019 to 2025). "Among women with BMI ≥ 30 kg/m2, the minor TT genotype of FER rs10447248 had an elevated breast cancer risk." (PMID 34367982, 2021). "When we stratified the analysis by WHR status, different patterns were observed for the association between FER rs10447248 (T/C) and breast cancer risk." (PMID 34367982, 2021). "This is consistent with the reported role of FER in breast carcinoma cells, in which FER downregulation causes increases in the G0/G1 cell fractions, with concomitant decreases in S-phase cells." (PMID 30909648, 2019). "This suggests that FER rs10447248 may predispose breast cancer by inducing NF-κβ and IL-6 to trigger downstream signaling pathways." (PMID 34367982, 2021). "FER tyrosine kinase increases NF-κβ activation and signals interleukin-6 (IL-6) to regulate STAT3 phosphorylation, which may explain its relationship with breast cancer risk through adiponectin and obesity." (PMID 34367982, 2021).
iron deficiency (3 papers, 2016 to 2022). "The FER-null mutant T3238fer, which was caused by the insertion of a Ty1-copia-like element in the first exon of FER, lost the whole iron deficiency responses." (PMID 31297128, 2019). "The first bHLH TF, which is characterized by its function in response to iron deficiency, is an Ib subgroup bHLH TF FER in tomato." (PMID 26801352, 2016).
pneumonia (3 papers, 2017 to 2025). An acute, acute and chronic, or chronic inflammation focally or diffusely affecting the lung parenchyma, caused by an infection in one or both of the lungs (by bacteria, viruses, fungi, or mycoplasma.). "Because severe pneumonia is the main cause of acute respiratory distress syndrome (ARDS), we aimed to investigate the effect of the FER polymorphism rs4957796 on the 90-day survival in patients with ARDS due to pneumonia." (PMID 28851893, 2017). "In conclusion, FER rs4957796 might act as a prognostic variable for survival in patients with severe ARDS due to pneumonia." (PMID 28851893, 2017).
colon carcinoma (2 papers, 2021 to 2024). "Downregulation of FER inactivated STAT3 in colon carcinoma cells." (PMID 34295819, 2021).
melanoma (2 papers, 2019 to 2022). A malignant, usually aggressive tumor composed of atypical, neoplastic melanocytes. "To investigate the role that FER kinase plays in melanoma growth, we generated FER-deficient melanoma lines using two different approaches." (PMID 30909648, 2019). "To investigate the role of FER kinase in melanoma, we developed two distinct FER loss-of-function models based on human melanoma cell lines that have the capacity to metastasize in vivo." (PMID 30909648, 2019). "We next examined the consequences of FER deficiency on the proliferative capacity of the melanoma lines we generated." (PMID 30909648, 2019). "Thus, FER depletion decreases melanoma tumor growth over time, and is associated with activation of melanin synthesis-associated pathways in subsets of FER-deficient cells in vivo." (PMID 30909648, 2019). "Collectively, our studies suggest that FER likely promotes melanoma metastasis through the sum of its effects on various distinct cellular pathways." (PMID 30909648, 2019). "Control and FER KO melanoma cells were transfected with TOPFlash or FOPFlash firefly luciferase reporter vectors containing, respectively, eight functional or mutated TCF/LEF binding sites." (PMID 30909648, 2019). "Similar results were observed in FER iKD melanoma cells, indicating that substantially reducing FER protein levels is sufficient to impair melanoma cell motility." (PMID 30909648, 2019). "We found that FER depletion in melanoma cells also disrupted the ability of the degradation-resistant β-catenin S33Y mutant to activate TCF/LEF activity." (PMID 30909648, 2019). "Collectively, our results show that FER positively modulates melanoma cell proliferation and motility, two processes that are essential for tumor progression and metastasis." (PMID 30909648, 2019). "Here, we have addressed the possibility that FER may be a broad regulator of tumorigenesis and have investigated its regulation of melanoma cell behavior." (PMID 30909648, 2019). "FER may contribute to melanoma metastasis through phosphorylation and consequent inhibition of the low-density lipoprotein receptor-related protein 6 (LRP6)." (PMID 30909648, 2019). "L1-CAM protein levels were similarly reduced in both FER iKD and FER KO melanoma cells, indicating that the extent of FER downregulation in response to silencing by shRNA treatment is sufficient to induce biological alterations that are very similar to those observed upon FER gene inactivation." (PMID 30909648, 2019). "In summary, our meta-analyses of 147 acral and 93 mucosal melanomas identified PTPRJ, FER, SKP2, LZTR1, CIC, and PRKN as part of a long tail of driver events that deserves further study and characterization." (PMID 35706047, 2022). "Pharmacological inhibitors for FER and SKP2 are available, and further investigation is needed to study their roles in acral and mucosal melanomas and determine whether they constitute therapeutic targets." (PMID 35706047, 2022). "Although this approach did not allow us to quantify subtle differences between tumor types, our results are consistent with the notion that normal FER protein levels are not required for melanoma invasion." (PMID 30909648, 2019). "Collectively, our data indicate that FER modulates processes involved in normal transit through S-phase, although it is not essential to maintain melanoma cells in an active proliferation state." (PMID 30909648, 2019). "Thus, FER positively modulates β-catenin/TCF-LEF-dependent transcription in melanoma cells, through mechanisms independent of β-catenin degradation or nuclear import." (PMID 30909648, 2019).
atherosclerosis (1 paper, 2022). A disease characterized by the build-up of fatty material and calcium deposition in the arterial wall resulting in partial or complete occlusion of the arterial lumen. "FER regulated cell–cell adhesion and absence of FER protein tyrosine kinase could induce epithelial barrier dysfunction which was regarded as a hallmark of many human panvascular diseases, including atherosclerosis, hypertension and diabetes." (PMID 36539828, 2022).
clear cell renal cell carcinoma (1 paper, 2013). "FER tyrosine kinase (FER) has been demonstrated to play a critical role in tumorigenesis and metastasis; however, its potential value as a novel prognostic marker for clear cell renal cell carcinoma (ccRCC) remains unclear." (PMID 23420638, 2013).
endometrial cancer (1 paper, 2025). Primary or metastatic malignant neoplasm involving the endometrium (mucous membrane that lines the endometrial cavity).
migraine (1 paper, 2024). "We further found drugs targeted for another six proteins (CSK, FER, GP1BA, PLCG1, PLG, and SERPING1), although currently there are no indications for migraine." (PMID 38898596, 2024).
ovarian tumor (1 paper, 2022). "This kinase-substrate regulatory mode between FER and IRS4, which leads to PIK3R2 recruitment and AKT activation, is critical for ovarian tumor cell growth." (PMID 35550247, 2022).
pancreatic cancer (1 paper, 2019). "Collectively, YY1 inhibits FER expression, which in turn results in impaired STAT3-MMP2 pathway leading to suppression of pancreatic cancer growth." (PMID 31824839, 2019).
severe combined immunodeficiency (1 paper, 2021). Severe combined immunodeficiency (SCID) comprises a group of rare monogenic primary immunodeficiency disorders characterized by a lack of functional peripheral T lymphocytes resulting in early-onset severe respiratory infections and failure to thrive. "Using GeneCards and MalaCards, showed EFNA5, FBXL17, and FER have been associated with severe combined immunodeficiency characterized by sensitivity to ionizing radiation disease, DNA damage response after ionizing radiation and activation of the ataxia-telangiectasia mutated protein, respectively." (PMID 34838041, 2021).